NR3C1 (nuclear receptor subfamily 3 group C member 1)
Diseases named in the same sentence as NR3C1 in open-access papers (continued):
Sharing a sentence is not in itself a finding about the gene and the disease.
schizophrenia (continued). "In summary, in a systematic meta-analysis we detect up-regulation of FKBP5 and down-regulation of NR3C1 in cerebellum samples of individuals with schizophrenia, and negative correlation between their expression patterns." (PMID 33673722, 2021). "While we did not detect differential expression of FKBP5 or NR3C1 in peripheral blood of patients with schizophrenia when compared to healthy controls, it should be noted that the analysis was performed on a single gene expression dataset (13 schizophrenia vs. 8 controls)." (PMID 33673722, 2021). "In addition, significant differences in the level of NR3C1 expression between patients with schizophrenia or schizoaffective disorder and healthy controls have not been confirmed." (PMID 33284958, 2021).
multiple myeloma (17 papers, 2012 to 2025). "Dexamethasone and prednisone’s pro-apoptotic and anti-proliferative effects are blocked by genetic anomalies and/or mutations occurring in the glucocorticoid receptor NR3C1 in relapsed multiple myeloma patients." (PMID 37744361, 2023). "NR3C1, a glucocorticoid receptor, has been associated with poor response to treatment in multiple myeloma samples." (PMID 22709873, 2012). "Through these experiments, we discovered that myeloma cells with NR3C1 knockdown had reduced invasion, migration, and proliferation—all of which were critical for the malignant evolution of myeloma." (PMID 40406148, 2025). "The mRNA as well as protein expression levels were found to be significantly reduced after NR3C1 knockdown in myeloma cells using qRT-PCR assay." (PMID 40406148, 2025). "For lymphoid cancers, acute lymphoblastic leukemia, chronic lymphocytic leukemia and multiple myeloma, NR3C1 activation has been proven to be an effective treatment strategy." (PMID 36468011, 2022). "NR3C1 not only played an important role in the proliferation and differentiation of myeloma cells, but might also affect tumor growth and progression by regulating cellular metabolic pathways." (PMID 40406148, 2025). "Therefore, we chose NR3C1 as a target and observed the changes in migration and proliferation ability of myeloma cells by knocking down NR3C1." (PMID 40406148, 2025). "The proliferation and spread of myeloma cells might be facilitated by the elevated expression of NR3C1." (PMID 40406148, 2025). "In C0 IGLC3+ myeloma cells, NR3C1 exhibited strong regulatory activity, indicating that it might be crucial for controlling cell division and proliferation in this subpopulation." (PMID 40406148, 2025). "The NR3C1-targeting miR-130b was found to exhibit higher expression in a glucocorticoid-insensitive multiple myeloma cell line, and its introduction into a glucocorticoid-sensitive line impaired the cellular response to glucocorticoid treatment, including the induction of apoptosis." (PMID 34986816, 2022). "The results showed that KLF6, NR3C1, IRF7 and YY1 were all actively regulated in C0 IGLC3+ Myeloma Cells, C1 IGHA1+ Myeloma Cells, and JUN was actively regulated in C0 IGLC3+Myeloma Cells, C1 IGHA1+ Myeloma Cells and C3 IGHG4+ Myeloma Cells." (PMID 40406148, 2025). "Next, we further analyzed the regulatory activity of TOP5 TF of C0 IGLC3+ Myeloma cells, and we visualized the expression of KLF6, NR3C1, IRF7, YY1 and JUN in all cells and different tissue sources." (PMID 40406148, 2025). "We analyzed the regulatory activity of TOP5 TFs in C0 IGLC3+ Myeloma cells and found that KLF6 was actively regulated in MM, and IRF7 and NR3C1 might be active in MM." (PMID 40406148, 2025). "Studies on the genetic background of patients with multiple myeloma (MM) have been increasing; two important factors considered in such works are uncoupling protein-2 (UCP-2) and nuclear receptor subfamily 3 group C member 1 (NR3C1)." (PMID 34481515, 2021).
anxiety disorder (16 papers, 2012 to 2025). A category of psychiatric disorders which are characterized by anxious feelings or fear often accompanied by physical symptoms associated with anxiety. "Childhood adversity and a history of past substance-use disorder and current or past depressive or anxiety disorders were associated with lower levels of NR3C1 promoter methylation across the region as a whole and at individual CpG sites (P<0.05)." (PMID 27378548, 2016). "The aim of the present study was to evaluate the role of NR3C1 haplotypes in mood and anxiety disorders." (PMID 25009637, 2014). "Methylation rates of NR3C1 exon 1F region are closely related to trauma exposure, adversity, nonabuse suicide, and anxiety disorders." (PMID 35968502, 2022). "With our association study in a cohort of pregnant women without further risk factors for depressive or anxiety disorders, we could not show that candidate single nucleotide polymorphisms within the genes FKBP5, NR3C1, and CRHR1 are associated with EPDS values during or after pregnancy." (PMID 24741566, 2014).
Cognitive impairment (16 papers, 2016 to 2026). Abnormal cognition is characterized by deficits in thinking, reasoning, or remembering. "In a previous study, the polymorphisms in 11 훽 -HSD type 1 and NR3C1 Bcl1 genes influenced the severity of cognitive impairments in processing and reading speed, auditory attention and working memory together with fatigue." (PMID 31253144, 2019). "Higher methylation of the NR3C1 gene might be related to cognitive impairment observed in this clinical population." (PMID 33284958, 2021).
metabolic syndrome (16 papers, 2009 to 2025). A cluster of metabolic risk factors for CARDIOVASCULAR DISEASES and TYPE 2 DIABETES MELLITUS. "A multivariate analysis revealed that the NR3C1 Bcl1 G allele was a significant risk factor for the prevalence of dyslipidemia (odds ratio = 4.6; 95% confidence interval = 1.8–12.2)." (PMID 25944971, 2015). "Further studies with a larger number of subjects are needed to validate the genetic risk factors associated with the prevalence of dyslipidemia and, in particular, the association of NR3C1 Bcl1 genotypes." (PMID 25944971, 2015). "Multivariate analyses of the genotype data further supported the correlation of the presence of the NR3C1 Bcl1 G allele (odds ratio, 4.671, P = 0.025) with dyslipidemia." (PMID 25944971, 2015). "The frequency of dyslipidemia was significantly higher in patients with the glucocorticoid receptor (NR3C1) Bcl1 G allele than in those with the CC genotype (P = 0.001)." (PMID 25944971, 2015). "In the univariate analysis, female gender, dose per body weight of steroid and MMF, and NR3C1 Bcl1 G allele were associated with dyslipidemia." (PMID 25944971, 2015). "In this study, 60 polymorphisms in 38 genes were examined, from which the frequency of the G allele in the NR3C1 Bcl1 gene was found to be higher in patients with dyslipidemia." (PMID 25944971, 2015). "Additionally, NR3C1 Bcl1 GG genotype was significantly associated with an increased risk of metabolic syndrome and high BMI in Chinese population." (PMID 25944971, 2015). "However, the frequency of the NR3C1 Bcl1 G allele was found to be higher in patients having dyslipidemia and therefore may be a putative genetic marker for predicting risk of the disease." (PMID 25944971, 2015). "The regulation of the hypothalamic-pituitary-adrenal (HPA) axis is associated with polymorphisms and the methylation degree of the glucocorticoid receptor gene (NR3C1) and is potentially involved in the development of metabolic syndrome (MetS)." (PMID 37761945, 2023). "Within non-European background, in Chinese population, NR3C1 rs770144345 was significantly associated with a higher risk of metabolic syndrome and CC alleles of IL-6 rs152410746 had a higher risk of developing nephropathy in T2DM subjects." (PMID 33542408, 2021). "Patients with dyslipidemia had a significantly higher frequency of the NR3C1 Bcl1 G allele (dyslipidemia, 25, nondyslipidemia, 23) than in those with the CC genotype (dyslipidemia, 19, nondyslipidemia, 59) (P = 0.001)." (PMID 25944971, 2015). "Although the mechanism by which the NR3C1 Bcl1 G allele might be involved in the prevalence of dyslipidemia is not clear, the analysis of dyslipidemia-related polymorphisms may provide a means to predict patient's risk for having dyslipidemia." (PMID 25944971, 2015). "Considering the variability in the prevalence of obesity and metabolic syndrome (MetS) in adult CAH patients, our aim was to evaluate whether NR3C1 polymorphisms could account for the development of this adverse metabolic profile in a series of CAH patients from same center." (PMID 23028665, 2012).
type 2 diabetes (16 papers, 2007 to 2025). "The SNP of NR3C1 is correlated with difficult-to-treat rhinosinusitis, glucose metabolism type 2 diabetes, and IgA nephropathies." (PMID 39920787, 2025). "Activation of expression of NR3C1 within the liver may contribute to the development of type 2 diabetes in mice and it has a role in liver glucose metabolism during fasting and in diabetic mice." (PMID 17428330, 2007).
Borderline personality disorder (15 papers, 2014 to 2025). A personality disorder characterized by impulsive behavior and unpredictable, capricious mood. "For example, hypermethylation of the NR3C1 gene, which encodes the glucocorticoid receptor, has been observed in patients with borderline personality disorder, suggesting a potential disruption in the hypothalamic–pituitary–adrenal (HPA) axis." (PMID 40722851, 2025). "(2015) reported that DNA methylation in the glucocorticoid receptor gene NR3C1 not only associated with depressive or borderline personality disorder symptoms but was also moderated by childhood maltreatment." (PMID 28480579, 2017). "In contrast, a study focused on women with histories of maltreatment and borderline personality disorder found that a history of maltreatment, and particularly of sexual and emotional abuse, was associated with greater methylation of the promoter region of the NR3C1 gene." (PMID 26074844, 2015). "They found significantly higher methylation of NR3C1 at specific exon 1C sites in BN patients with comorbid borderline personality disorder or suicidality compared to normal controls." (PMID 40282388, 2025). "The results showed that patients with borderline personality disorder, who had a significantly higher rate of childhood abuse, had significantly higher NR3C1 methylation than patients with MDD." (PMID 24465557, 2014). "Similarly, increased DNA methylation of NR3C1 is observed in blood of patients with borderline personality disorder (BPD)." (PMID 27918480, 2016). "Interestingly, NR3C1 was most investigated in BPD (-> Borderline Personality Disorder)." (PMID 30510522, 2018). "One of the previous studies measured NR3C1 methylation in patients with borderline personality disorder and MDD, but healthy controls were not included in the study." (PMID 24465557, 2014).
leukemia (15 papers, 2012 to 2025). A malignant (clonal) hematologic disorder, involving hematopoietic stem cells and characterized by the presence of primitive or atypical myeloid or lymphoid cells in the bone marrow and the blood. "The mean mRNA expression of NR3C1 in ALL cells of patients in the good-responder cohort was 3.3-fold higher than in R/R leukemia cells (p < 0.01)." (PMID 31462891, 2019). "The concentration of NR3C1 protein in ALL cells of patients in the good-responder cohort was higher than in R/R leukemia cells according to western blotting analysis." (PMID 31462891, 2019). "Glucocorticoid receptor (NR3C1) signaling, activated by dexamethasone, a known treatment for leukemia, was found to be negligible change, aligning with the observed negative control of genes regulated by dexamethasone in EF-24–treated HL-60 cells." (PMID 40986633, 2025).
ovarian carcinoma (15 papers, 2013 to 2025). A malignant neoplasm originating from the surface ovarian epithelium. "It has been demonstrated that NR3C1 plays a vital role in the development of various malignancies, such as triple-negative breast cancer, ovarian cancer, and urothelial cancer." (PMID 37807060, 2023). "Moreover, high levels of NR3C1 mRNA expression have been correlated with aggressive clinical features and poor prognosis in ovarian cancer." (PMID 39273521, 2024). "Numerous studies have confirmed that NR3C1 can promote tumor proliferation, metastasis and drug resistance by up-regulating ROR-1 or NF-κB in various malignancies, such as triple-negative breast cancer, ovarian cancer, and urothelial cancer." (PMID 37807060, 2023).
acute lymphoblastic leukemia (14 papers, 2017 to 2025). Leukemia with an acute onset, characterized by the presence of lymphoblasts in the bone marrow and the peripheral blood. "In lung cancer and childhood acute lymphoblastic leukemia, NR3C1 genetic variants were significantly associated with the cancer susceptibility." (PMID 29285253, 2017). "In addition, the mutation of NR3C1 may lead to glucocorticoid resistance and lead to treatment failure and recurrence of acute lymphoblastic leukaemia." (PMID 35069971, 2022). "Studies have confirmed that the deletion of NR3C1 is one of the reasons for the failure of acute lymphoblastic leukaemia induction." (PMID 35069971, 2022). "NR3C1 also plays an important role in acute lymphoblastic leukaemia." (PMID 35069971, 2022). "MiR-124 exhibits varied roles in different cancer types, with upregulation observed in Acute Lymphoblastic Leukemia (ALL), contributing to glucocorticoid resistance by suppressing the Glucocorticoid Receptor (NR3C1)." (PMID 38612567, 2024).
atherosclerosis (14 papers, 2012 to 2025). A disease characterized by the build-up of fatty material and calcium deposition in the arterial wall resulting in partial or complete occlusion of the arterial lumen. "Anomalies concerning the NR3C1 gene, implicated in the atherosclerosis process and associated with heart disease, were observed in adult victims of abuse and child abuse." (PMID 34356253, 2021). "With respect to ACS, hypermethylation of NR3C1 has been found to be associated with atherosclerosis and elevated cardiovascular reactivity." (PMID 32218512, 2020). "Hence, variants of the NR3C1 gene may affect the development and progression of CA atherosclerosis." (PMID 36009459, 2022). "The network with regulator NR3C1 was activated, inhibiting TGFB3, which is involved in the pathogenesis of atherosclerosis via TGF-β signaling." (PMID 35925965, 2022).
glioblastoma (13 papers, 2013 to 2026). The most malignant astrocytic tumor (WHO grade IV). "Recent research has shown that Rg5 inhibits glioblastoma progression by activating nuclear receptor subfamily 3 group C member 1 (NR3C1), thereby regulating heat shock protein family B member 1 (HSPB1) and nuclear receptor coactivator 4 (NCOA4)." (PMID 40552277, 2025). "NR3C1 can act as a direct target of ginsenoside Rg5 to regulate the expression levels of HSPB1 and NCOA4 and inhibit glioblastoma progression." (PMID 40995432, 2025).
stress-related disorder (12 papers, 2012 to 2025). Stress-related disorders are mental health disorders that are a result of an atypical response to both short and long-term anxiety due to physical, mental, or emotional stress. "For instance, DNA methylation in the glucocorticoid receptor gene (NR3C1) in adulthood is known to be associated with early-life adversities and has been suggested to mediate the development of stress-related disorders." (PMID 29921868, 2018). "Above to DNA methylation changes within NR3C1, hypo- or hyper-methylation within other genes have been found to play a key role in mediating the impact of early life stress on the development of stress-related disorders, including BPD." (PMID 28619017, 2017). "Recent studies have further elucidated the role of nr3c1 methylation in stress-related disorders." (PMID 40243462, 2025).
glucocorticoid resistance (11 papers, 2014 to 2024). "At present time, primary generalized glucocorticoid resistance has been exclusively associated with defects in the NR3C1 gene." (PMID 38433539, 2024). "Glucocorticoid resistance is commonly observed in depression, and has been linked to reduced expression and/or function of the glucocorticoid receptor (NR3C1 in human, hereafter referred to as GR)." (PMID 37525888, 2023). "A previous study also found that chronic stress impaired the negative feedback of corticosterone in the HPA axis by down-regulating the glucocorticoid receptors (Nr3c1), leading to glucocorticoid resistance, which is also coincident with a high level of inflammation." (PMID 37139495, 2023).
mood disorder (11 papers, 2012 to 2025). A cognitive disorder a disturbance in which the person's mood is hypothesized to be the main underlying feature. "On cross-sectional analysis, there was evidence of higher methylation rates for BDNF-1 in high-risk offspring affected (n = 27) and unaffected (n = 23) for mood disorder compared to controls (n = 24) and higher methylation rates in affected high-risk offspring for NR3C1 compared to controls." (PMID 31385059, 2019). "Specifically, genes, such as NR3C1, SLC6A4, BDNF, FKBP5, SKA2, and OXTR, exhibit alterations in DNA methylation patterns that are frequently linked to mood disorders." (PMID 38792892, 2024). "This study supports previous reports of differences in the expression of IL8 and NR3C1 amongst mood disorder patients." (PMID 24618828, 2014). "Moreover the level of BDNF with SLC64 is utilized as a biomarker to diagnose mood disorders in diseased/healthy subjects, and there are many other genes (NR3C1 and FKBP5) that have also been linked to the early diagnosis of mood disorders." (PMID 36766442, 2023). "Furthermore, there was higher mean methylation percentages in HR offspring affected for mood disorder compared to controls for NR3C1." (PMID 31385059, 2019).
bipolar disorder (10 papers, 2012 to 2025). A disorder of the brain that causes unusual shifts in mood, energy, activity levels and the ability to carry out day-to-day tasks. "It has been shown that three polymorphisms (rs6198, rs6191, and rs33388) within the NR3C1 resulting in GR resistance are associated with major depression and the predominance of depression in the course of bipolar disorder." (PMID 28096796, 2016). "This implies a positive regulation of KITLG gene to NR3C1 expression, a key gene in the stress response, that in term plays a role in bipolar disorder and the response to trauma." (PMID 30723428, 2018). "In this study, we identified abnormalities of GR mRNA expression in schizophrenia and bipolar disorder, which we describe for first time in the context of variation within the NR3C1 gene." (PMID 22427805, 2012). "Additionally it has been demonstrated that increased Nr3c1 promoter methylation levels obtained from peripheral blood samples of bipolar disorder, manic depressive disorder, and PTSD subjects correlate with the severity of childhood abuse." (PMID 23847551, 2013). "A putative link between KITLG function and bipolar disorder is that the ligand of the C-kit receptor (SCF), is involved in hematopoiesis, neurogenesis, and neuroprotection and induces glucocorticoid receptor gene (NR3C1) expression in response to stress induced erythropoiesis." (PMID 30723428, 2018).
fatty liver disease (10 papers, 2017 to 2025). A reversible condition wherein large vacuoles of triglyceride fat accumulate in liver cells via the process of steatosis. "A “HES1-NR3C1 axis” was identified in elevated glucocorticoid-induced fatty liver disease, e.g. NR3C1 directly inhibited HES1 promoter transcription via negative GRE12." (PMID 28674421, 2017).